ATXN3L (ataxin 3 like)
Description:
Deubiquitinating enzyme that cleaves both 'Lys-48'-linked and 'Lys-63'-linked poly-ubiquitin chains (in vitro). Acts as a deubiquitinating enzyme for the transcription factor KLF5, playing a role in the regulation of KLF5 stability.
Synonyms: MJDL; ATXN3L1
Tractability: Small molecule: it has a binding pocket of medium quality.
Target class: Enzyme; Hydrolase
Gene: Protein-coding gene on chromosome X (13,318,647 to 13,320,053, reverse strand). Ensembl gene ENSG00000123594.
Subcellular location: Nucleus
Pathways (Reactome):
Metabolism of proteins: Josephin domain DUBs
Gene Ontology:
Molecular function: cysteine-type deubiquitinase activity
Biological process: protein deubiquitination; negative regulation of TORC1 signaling; positive regulation of ERAD pathway; proteasome-mediated ubiquitin-dependent protein catabolic process; protein quality control for misfolded or incompletely synthesized proteins
Cellular component: cytosol; nucleus
Homologues: Orthologues: mouse Atxn3 (66% identical), rat Atxn3 (65% identical), tropical clawed frog atxn3 (54% identical), zebrafish atxn3 (50% identical), Caenorhabditis elegans atx-3 (28% identical). Paralogues in human: ATXN3 (70% identical).
Diseases named in the same sentence as ATXN3L in open-access papers:
ATXN3L is named in the same sentence as 12 diseases in open-access papers, as found by Europe PMC text mining. Sharing a sentence is not in itself a finding about the gene and the disease. The quoted sentences say what the papers report.
breast carcinoma (5 papers, 2015 to 2024). "Three DUBs, including ATXN3L, BAP1, and USP3 can deubiquitinate and stabilize KLF5 that are implicated in the pathological development of breast cancer." (PMID 38468288, 2024). "Consistently, knockdown of ATXN3L by shRNAs significantly decreased cell proliferation in both breast cancer cell lines, as measured by CCK-8." (PMID 26079537, 2015). "Functionally, depletion of ATXN3L increased the p27 and p21 protein levels and suppressed breast cancer cell proliferation." (PMID 26079537, 2015). "Since ATXN3L stabilizes KLF5 and inhibits the expression of p27 and p21, it is plausible that ATXN3L also promotes breast cancer cell proliferation." (PMID 26079537, 2015). "In summary, our study identified ATXN3L as a KLF5 DUB in breast cancer and found that ATXN3L stabilized the KLF5 protein and promoted cell proliferation partially through KLF5." (PMID 26079537, 2015). "Our findings uncovered a new regulatory mechanism for KLF5 and suggest that ATXN3L is a potential therapeutic target for breast cancer treatment." (PMID 26079537, 2015). "It is possible that ATXN3L serves as a novel therapeutic target for breast cancer and other cancer patients." (PMID 26079537, 2015). "Besides UCHL1, some other DUBs, such as ATXN3L, BAP1, and USP3 can deubiquitinate KLF5 and are implicated in the pathological development of breast cancer." (PMID 38468288, 2024). "Down-regulation of ATXN3L suppresses breast cancer cell proliferation by directly binding to KLF5." (PMID 36159990, 2022). "Previous research reported that ATXN3L was expressed at higher levels in breast cancer." (PMID 36159990, 2022). "To further confirm whether ATXN3L knockdown decreases KLF5 protein stability in human breast cancer cells, we knocked down ATXN3L in HCC1806 and SUM1315 (two basal type triple negative breast cancer cell lines), in which KLF5 is highly expressed." (PMID 26079537, 2015). "Functionally, knockdown of ATXN3L inhibits breast cancer cell proliferation partially through KLF5." (PMID 26079537, 2015). "Hence, ATXN3L might be a potential therapeutic target for breast cancer." (PMID 38129384, 2023). "Nevertheless, ATXN3L increased the KLF5 protein stability and inhibited the expression of KLF5 downstream target genes, such as p21 and p27, and promote basal type breast cancer cell proliferation." (PMID 26079537, 2015). "We identified ATXN3L as a candidate KLF5 DUB because knockdown of ATXN3L decreased KLF5 protein levels and inhibited breast cancer cell proliferation." (PMID 26079537, 2015). "However, the function of ATXN3L in breast cancer is unknown." (PMID 26079537, 2015). "In reviewing the literature, no data were found on the association of breast cancer with PCGF1, RNF123, GRWD1, USP30, ATXN3L, and PARP11." (PMID 36685836, 2022). "Using RT-qPCR, we measured the ATXN3L mRNA levels in a panel of breast cancer cell lines and tumors but failed to observe any significant expression changes between normal and cancer samples." (PMID 26079537, 2015).
breast tumors (1 paper, 2015). "Since ATXN3L regulates KLF5 at the protein level, it will be significant to develop a good anti-ATXN3L Ab to examine the ATXN3L protein expression in breast tumors in order to assess the clinical relevance of ATXN3L." (PMID 26079537, 2015).
hepatocellular adenoma (1 paper, 2022). A benign epithelial neoplasm arising from the hepatocytes. "The sub-types of with the highest proprotion of all alterations were Hepatocellular carcinoma plus Intrahepatic Cholangiocarcinoma, Hepatocellular Adenoma, and Hepatocellular carcinoma for ATXN3, ATXN3L, JOSD1, and JOSD2, respectively." (PMID 36159990, 2022).
lymph node metastasis (1 paper, 2022).
Machado-Joseph disease (1 paper, 2024). "ATXN3L is a deubiquitinating enzyme expressed in brain and associated with Machado-Joseph disease." (PMID 38730027, 2024).
testicular tumors (1 paper, 2022). "Our results showed that ATXN3, JOSD1, and JOSD2 were markedly up-regulated in HCC samples, while ATXN3L was expressed only in testicular and testicular tumors." (PMID 36159990, 2022).
ATXN3L also shares sentences with these, for which no sentence is quoted: cancer (2 papers); hepatocellular carcinoma (1); intrahepatic cholangiocarcinoma (1); Spinocerebellar ataxia type 3 (1); triple-negative breast carcinoma (1); tumor (1).